GPR158 (G protein-coupled receptor 158)
Diseases named in the same sentence as GPR158 in open-access papers (continued):
Sharing a sentence is not in itself a finding about the gene and the disease.
tumor (10 papers, 2015 to 2025). "Through RNA-Seq analysis of HNSCC samples (3 tumors and 3 para-carcinoma tissues), we identified 8 pivotal marker genes (PCDH7, CDH2, ITGA3, SEMA7A, TMEM132A, CD276, TMEM2, GPR158) that were overexpressed in tumor specimens." (PMID 38548747, 2024). "GPR158 expression correlates with a neuroendocrine differentiation phenotype and promotes anchorage-independent colony formation implying a role for GPR158 in tumor formation." (PMID 35456013, 2022). "It was also found that GPR158 can interact with androgen receptors to modulate tumor cell proliferation via lowering the responding threshold to androgen during androgen deprivation therapy." (PMID 35456013, 2022). "The GPR158 protein was mainly localized to the cytoplasm of tumor cells, but occasional staining was also found in tumor cell nuclei." (PMID 31533654, 2019). "As reported here, GPR158 was mainly localized in the cytoplasm of tumor cells, with occasional staining in the nuclei of tumor cells." (PMID 31533654, 2019). "Next, we separated the 85 NHNN patients of whom we had tissue stainings into two groups according to the GPR158 stain score (above and below median), and found that patients whose tumours expressed higher levels of GPR158 survived longer (p < 0.05)." (PMID 29720725, 2018). "Under these conditions, GPR158 induces neural, glial and neuronal phenotypes and apoptosis in tumour spheres and cells and in allografts in vivo." (PMID 29720725, 2018). "There was a strong correlation between GPR158 expression level and survival across all tumours (p = 1.65E-21)." (PMID 29720725, 2018). "Patients with high GPR158 expression were younger than those with low expression, consistent with IDH mutant tumours occurring in younger patients are also being associated with better survival." (PMID 29720725, 2018). "Of translational importance, miR-449a expression correlates with tumour grade and with poorer survival (p = 0.004), and consistent with our experimental data, GPR158 expression correlates with better prognosis and inversely with tumour grade." (PMID 29720725, 2018). "Our results indicate that increased GPR158 stimulates colony formation in the anchorage-independent soft agar assay, which is considered as an indicator of the capacity for tumor growth in vivo." (PMID 25693195, 2015). "We found that GPR158 mRNA was altered by 1.5-fold or higher in 9% of all the tumor cases, and it was upregulated in 8% of the cases examined." (PMID 25693195, 2015). "In all three prostate lobes: anterior (AP), ventral (VP) and dorsolateral (DLP), the level of GPR158 protein was remarkably higher in tumor tissues of the Pten-/- prostate, as compared with the normal prostate of the Pten+/+ mouse." (PMID 25693195, 2015). "Notably, GPR158 displays region- and cell type-specific bidirectional effects under certain pathological conditions, such as tumor development and mood regulation, adding complexity to its mechanisms of action." (PMID 40337551, 2025). "In addition, GPR158 expression was found to correlate with neuroendocrine (NE) differentiation phenotypes and promote anchor-independent colony formation, suggesting a role for GPR158 in treatment progression and tumor formation." (PMID 41347146, 2025). "The diverse effects of GPR158 in tumor cells may stem from its spatiotemporal expression patterns and expression levels." (PMID 40337551, 2025). "However, when we explored if Gpr158 regulates the ability of BTSC to form tumour spheres, we found in an extreme limiting dilution assay a significant reduction of sphere forming cells upon Gpr158 overexpression." (PMID 29720725, 2018).
tumor (continued). "Further, we found GPR158 expression correlates with a neuroendocrine (NE) differentiation phenotype and promotes anchorage-independent colony formation implying a role for GPR158 in therapeutic progression and tumor formation." (PMID 25693195, 2015). "Additionally, GPR158 promotes tumor cell proliferation and angiogenesis and may be negatively regulated by miR-613." (PMID 40337551, 2025). "miR-449a could be considered as druggable target, e.g., using antagomirs, and GPR158, a member of a large family of receptors may be targeted by pharmacological agents, e.g., by stimulating the downstream pathway of GPR158, to reduce tumour growth." (PMID 29720725, 2018). "Interestingly, increased GPR158 expression is observed at the leading edges of glands, where cancer cells are invading the surrounding stroma, suggesting that GPR158 up-regulation in Pten−/− PCa cells could contribute to tumor invasion." (PMID 25693195, 2015). "We observed enhanced GPR158 expression in areas of tumor cell invasion into the surrounding stroma and cells of the invading front showed the most intense staining in all three lobes (j-l), suggestive of in vivo contributions of GPR158 in tumorigenicity and invasion of PCa cells." (PMID 25693195, 2015). "Here we present evidence that GPR158 could play a part in both PCa tumor growth and NED." (PMID 25693195, 2015). "Given the paucity of literature exploring GPR158, it would require further evaluation in the form of expression quantification in both MOC and non-tumour tissue in order to further evaluate its potential as a theranostic." (PMID 34830751, 2021). "The difference of GPR158 expression levels was statistically significant between eGBM and GBM (p < 0.0001), suggesting that GPR158 was further down-regulated upon tumour progression to a higher (histological) grade." (PMID 29720725, 2018). "Staining of tumor tissues of 14 BCG responders and 18 failures with a GPR158-specific antibody was performed; however, tumors of both cohorts displayed varying degrees of GPR158 protein expression." (PMID 32764425, 2020).
cancer (5 papers, 2015 to 2024). A tumor composed of atypical neoplastic, often pleomorphic cells that invade other tissues. "Kaplan-Meier analysis on a dataset from the Memorial Sloan Kettering cancer genome portal showed that increased GPR158 expression in tumors is associated with lower disease-free survival." (PMID 25693195, 2015). "Importantly, the Kaplan-Meier analysis on the dataset from the Memorial Sloan Kettering cancer genome portal showed that increased GPR158 expression in tumors is associated with lower disease-free survival." (PMID 25693195, 2015). "Of note, a series of studies have been carried out involving GPCR 158 (or GPR158) since its identification in 2005, predominantly focusing on the characterization of its roles in the progression of cancer and mental illness." (PMID 35456013, 2022). "Studies have been carried out to uncover the molecular mechanisms of GPR158 in the vast complexity of cancer phenotypes and genotypes." (PMID 35456013, 2022). "In this review, we address the current status of research on GPR158, specifically its roles in cancer and mental illness." (PMID 35456013, 2022). "In conclusion, increase of GPR158 expression in mBTSC and hBTSC reduces proliferation, migration and cancer stem cell formation, upregulation of proneural markers and induction of apoptosis whilst downregulation of GPR158 has the opposite effect." (PMID 29720725, 2018). "Using Oncomine, an online cancer-profiling database, we performed a search for expression microarray datasets that included GPR158." (PMID 25693195, 2015). "However, the functions of GPR158 are still largely unknown, although studies indicate an emerging key role in the nervous system and in cancer." (PMID 35456013, 2022).
endocrine diseases (1 paper, 2022). "Despite studies on GPR158 being underway, existing studies suggest that GPR158 might be a potential target for endocrine diseases." (PMID 36467406, 2022).
GPR158 also shares sentences with these, for which no sentence is quoted: cognitive disease (2 papers); glioblastoma (2); mental illnesses (2); oligodendroglioma (2); age-onset diseases (1); Atrophy (1); cardiac diseases (1); clear-cell ovarian carcinoma (1); dementia (1); frontotemporal dementia (1); infarction (1); low grade glioma (1); melanoma (1); memory loss (1); mucinous ovarian carcinoma (1); neurodegenerative disease (1); neuroendocrine neoplasm (1); neurological diseases (1); paraganglioma (1); pheochromocytoma (1); stress-related disorder (1); Stroke (1).